NUGGC (nuclear GTPase, germinal center associated)
Description:
Nuclear GTPase found in germinal center B-cells, where it may inhibit function of the activation-induced cytidine deaminase AICDA. Reduces somatic hypermutation in B-cells which may enhance genome stability (By similarity).
Synonyms: C8orf80; HMFN0672; SLIP-GC; SLIPGC
Tractability: No criterion of Open Targets' tractability assessment is met for any kind of drug.
Gene: Protein-coding gene on chromosome 8 (28,021,964 to 28,083,936, reverse strand). Ensembl gene ENSG00000189233.
Subcellular location: Nucleus speckle
Subcellular location (Human Protein Atlas): Nuclear speckles; Cytosol; Nucleoplasm
Gene Ontology:
Molecular function: GTPase activity
Biological process: cellular response to lipopolysaccharide; negative regulation of apoptotic process; regulation of nuclear cell cycle DNA replication
Cellular component: nuclear speck; nucleus
Genetic constraint (gnomAD): Loss-of-function variants: 32 observed, 56.29 expected, observed/expected ratio (o/e) 0.57, 90% interval 0.43 to 0.76. The upper end of that interval is the gene's LOEUF score, 0.76, which puts it in group 3 of 6, group 1 being the genes least tolerant of losing a copy. Missense variants: 705 observed, 738.52 expected, observed/expected ratio (o/e) 0.95, 90% interval 0.9 to 1.02. Synonymous variants: 291 observed, 286.35 expected, observed/expected ratio (o/e) 1.02, 90% interval 0.92 to 1.12.
Homologues: Orthologues: chimpanzee NUGGC (99% identical), macaque NUGGC (97% identical), pig NUGGC (86% identical), dog NUGGC (85% identical), guinea pig NUGGC (81% identical), rabbit NUGGC (78% identical), zebrafish nuggc.1 (21% identical), zebrafish nuggc.3 (20% identical), zebrafish nuggc.2 (12% identical), zebrafish si:dkeyp-85e10.3 (6% identical).
Diseases named in the same sentence as NUGGC in open-access papers:
NUGGC is named in the same sentence as 9 diseases in open-access papers, as found by Europe PMC text mining. Sharing a sentence is not in itself a finding about the gene and the disease. The quoted sentences say what the papers report.
immunodeficient diseases (1 paper, 2022). "The functional capacities of the highly expressed DEGs in the Chinese Simmental cattle mainly focused on inflammatory diseases (CXCL9 and FCRL1), immunodeficient diseases (ADM2, CCL5, and CAMKV), carcinoma (CXCL11, JAKMIP2, GZM, and DNAAF1), and GTP binding and GTPase activity (NUGGC)." (PMID 35495650, 2022).
Inguinal hernia (1 paper, 2025). Protrusion of the contents of the abdominal cavity through the inguinal canal. "However, it should be pointed out that certain CNVs, particularly CNV SSC14: 13,030,843 bp – SSC13059455 bp, showed a significant association with UH in Duroc pigs, specifically affecting the NUGGC gene, which is known to be implicated in human omphalocele and inguinal hernia." (PMID 41257561, 2025).
melanoma (1 paper, 2020). A malignant, usually aggressive tumor composed of atypical, neoplastic melanocytes. "According to the melanoma SCRS data, all mir-149 targets identified were expressed in lymphocytes, some of which were exclusively expressed in this cell type and include CD96, CD48, SLAMF7, FASLG, NUGGC and NLRC5." (PMID 32024530, 2020).
Obesity (1 paper, 2021). Accumulation of substantial excess body fat. "Among these obesity-associated genes, three genes (NUGGC, EFR3B, and SOX4) were found to be upregulated or downregulated according to the presence of obesity both in the literature and in the current study." (PMID 34381138, 2021).
infection (1 paper, 2020). The state of being infected such as from the introduction of a foreign agent such as serum, vaccine, antigenic substance or organism. "In addition, AICDA and NUGGC had previously been identified as displaying significant ≥ 2-fold increases in expression when comparing d28 pi to d0 LN samples from both infection groups combined." (PMID 32017809, 2020).
NUGGC also shares sentences with these, for which no sentence is quoted: cancer (2 papers); lymphoma (1); omphalocele (1); ovarian carcinoma (1).